CDK2 (cyclin dependent kinase 2)
Diseases named in the same sentence as CDK2 in open-access papers (continued):
Sharing a sentence is not in itself a finding about the gene and the disease.
gastric cancer (continued). "In a xenograft mouse model of gastric cancer, NRP1-depletion causes upregulation of p27 and downregulation of cyclin E and Cyclin-dependent kinase-2 (CDK-2) and, thus, cell cycle arrest in the G1/S phase." (PMID 30717262, 2019). "CDK2 partly mediated the promoting role of PCBP2 in human gastric cancer cells and the expression levels of PCBP2 and CDK2 were positively correlated in gastric cancer tissues." (PMID 29744291, 2018). "PCBP2 and CDK2 were positively correlated in gastric cancer tissues (Pearson's correlation coefficient: r = 0.1718, P = 0.029)." (PMID 29744291, 2018). "CDK2 is involved in cell cycle regulation by miR‐302b and promotes the progression of gastric cancer." (PMID 29744291, 2018). "In a further study, the expression of CDK2 in tissues from gastric cancer patients was examined by immunohistochemistry." (PMID 29744291, 2018). "Morusin markedly inhibited gastric cancer cell proliferation by down-regulating CDKs and Cyclins, such as CDK2, CDK4, Cyclin D1 and Cyclin E1." (PMID 28915664, 2017). "In accord, the present results have demonstrated that depletion of NRP-1 inhibited the proliferation of gastric cancer cells by inducing cell cycle arrest in the G1/S phase through upregulating p27 and downregulating cyclin E and CDK2." (PMID 26795388, 2016). "Our results showed that miR‐302b can target and negatively regulate the expression of CDK2 to decrease cell proliferation and arrest cell cycle in gastric cancer tissues via suppressing ERK signal pathway." (PMID 27465546, 2016). "This study aims to evaluate the relationship between miR‐302b and ERK signaling pathway, and the underlying molecular mechanisms by examining the expression of miR‐302b and CDK2, and their roles in gastric cancer cells." (PMID 27465546, 2016). "miR‐302b promoted the proliferation of gastric cancer cells through upregulation of CDK2, thereby inhibiting ERK pathway, which can in turn inhibit the promoting ability of miR‐302b on proliferation." (PMID 27465546, 2016). "Previous studies suggested that CDK2 was a positive regulator of gastric cancer cell cycle, which can be abnormally activated by increased degrees of malignancy and the invasion of cancer cells." (PMID 27465546, 2016). "Decreased miR‐302b and increased CDK2 expressions can significantly promote proliferation and G1/S phase transformation in gastric cancer." (PMID 27465546, 2016). "Decreased miR-29a-3p expression promoted gastric cancer cell proliferation via reducing the expression of cell-cycle regulators including: CDK2, CDK4, and CDK6." (PMID 25889078, 2015). "Growth inhibitory effect of celery seed extracts on human gastric cancer BGC-823 cells was determined, which was associated with cycle arrest in the S phase and decreased levels of cyclin A and CDK-2." (PMID 25401123, 2014). "Flavopiridol, a CDK1 and CDK2 inhibitor, is being clinically tested against gastric cancer, leukemia, and head and neck cancer." (PMID 23320178, 2012). "Additionally, DDX21 directly enhances gastric cancer progression by increasing the mRNA and protein of cyclin D1 and CDK2." (PMID 39769343, 2024). "Moreover, Poly (rC) binding protein 2 (PCBP2), acting as an oncogene in gastric cancer cells, promotes the CDK2 activity by direct interaction and is overexpressed in gastric cancer, where the higher expression is associated with poor survival of the patients." (PMID 36769170, 2023). "Another micro-RNA, miR-302b, targets CDK2 in gastric cancer cells through ERK signaling." (PMID 36769170, 2023). "CDK2 can regulate cell cycles and aerobic glycolysis in gastric cancer." (PMID 37007126, 2023). "Hence, the promoting role of PCBP2 in the viability of human gastric cancer cells was mediated by CDK2." (PMID 29744291, 2018).
gastric cancer (continued). "Moreover, we determined that CDK2 mediated the promoting role of PCBP2 in human gastric cancer cells." (PMID 29744291, 2018). "PCBP2 and CDK2 were positively correlated in gastric cancer tissues." (PMID 29744291, 2018). "Our data demonstrated that c-Myc up-regulated CDK2 expression, but the mechanism by which c-Myc up-regulated CDK2 expression in gastric cancer cells remains unclear." (PMID 28915664, 2017). "Furthermore, miR-638 in gastric cancer cells directly regulates the expression of CDK2." (PMID 36769170, 2023). "In addition, AST treated gastric cancer cells decreased the expression of pRb and CDK2." (PMID 32438569, 2020). "CDK2 might mediate the tumor‐promoting role of PCBP2 in human gastric cancer cells." (PMID 29744291, 2018). "Therefore, PCBP2 facilitated the viability of gastric cancer cells specifically by regulating CDK2." (PMID 29744291, 2018). "For example, enhanced expression of miR-29a can inhibit mucin 1 (MUC1), reducing the expression levels of cell cycle-dependent kinases CDK2, CDK4, and CDK6, leading to reduced proliferation of gastric cancer cells." (PMID 39519347, 2024). "in gastric cancer, wherein GSDMD is downregulated among different gastric cancer cell lines by inhibiting the cyclinA2/CDK2 complex and arresting into the S/G2 phase transition." (PMID 37819510, 2023). "Calcium/calmodulin-dependent protein kinase 2 (CAMKK2) works as an upstream factor for CDK1, CDK2, and ERK1 in gastric cancer, as evidenced by bioinformatics analysis." (PMID 36769170, 2023). "Cyclin E and CDK2 overexpression along with p57 (KIP2) regulation are important factors for metastasis and progression of gastric cancer." (PMID 36769170, 2023). "Subsequently, both EGR1 and HNF1A-AS1 inhibit p21 via activation of CDK2 and CDK4, adding another layer of regulatory mechanisms involved in the function of CDK2 in the development of gastric cancer." (PMID 36769170, 2023). "In gastric cancer (GC), pyroptosis can be inhibited by the downregulation of gasdermin D (GSDMD), which expedites the expression of Cdk2/cyclin A2 complexes." (PMID 37198617, 2023). "In gastric cancer, upregulated DDX21 increased cell proliferation in vitro and tumor progression in mice via the Cyclin D1 and CDK2 pathways." (PMID 35371306, 2022). "The constructed network pharmacology revealed the significant interaction among the predicted targets that led to the identification of three core proteins (CDK2, MMP1, and HSP90) as the active bio targets of PG in gastric cancer." (PMID 33921173, 2021). "A recent study on prunetinoside, a flavonoid derived from Prunus sp., revealed key targets in gastric cancer (heat shock protein 90 (HSP90), cyclin-dependent kinase 2 (CDK2), and MMP1), and cell docking analysis confirmed the potential of the molecule to bind to these targets." (PMID 40149274, 2025). "In gastric cancer, DDX21 has been shown to drive cancer cell proliferation, primarily through the activation of the cyclin D1 and CDK2 signaling pathways, suggesting that DDX21 could serve as a therapeutic target for gastric cancer." (PMID 39769343, 2024). "In gastric cancer cells, a long non-coding RNA named LINC01021, which is upregulated in cancer cells, functions in the regulation of KISS1, which is further stabilized via CDK2 activity." (PMID 36769170, 2023). "There is no clear relationship between c-Myc and CDK2 in rat cells, but in gastric cancer cells, c-Myc can up-regulate the expression of CDK2." (PMID 36674593, 2023).
gastric cancer (continued). "This disagreement may be due to forced GSDMD overexpression, which can reverse gastric cancer cell proliferation by inactivating the ERK, STAT3, and PI3K/AKT pathways, and then inhibiting the Cyclin A2/CDK-2 complex to arrest the S/G2 phase transition." (PMID 36120543, 2022). "Additionally, another study showed that the levels of Bcl-2, cyclin A1, and CDK2 were downregulated, and Bax expression was upregulated by overexpression of RSK4 in gastric cancer cells, which is consistent with the results of our study." (PMID 36031631, 2022). "In the 100 gastric cancer tissues and 100 adjacent nontumorous tissues, CDK2 exhibited a higher protein level in gastric cancer tissues compared to adjacent nontumorous tissues." (PMID 29744291, 2018). "Finally, correlation analysis revealed that FEZF1-AS1expression levels were positive correlation with SP1 and CDK2/CDK4/CDK6/CyclinD1 and inversely correlated with P21 expression levels in Gastric Cancer tissues." (PMID 28209170, 2017). "Furthermore, another gastric cancer promoter protein named a DEAD cassette helicase 21 (DDX21), which is an ATP-dependent RNA helicase, is involved in upregulating the expression of Cyclin D1 and CDK2." (PMID 36769170, 2023). "GSDMD reduces the expression of Cyclin A2 and Cyclin-Dependent Kinase (CDK2) by inhibiting ERK1/2, STAT3, and PI3K/Akt in gastric cancer (GC) cells." (PMID 35963853, 2022). "In addition, we have shown that the protein levels of CDK2 were dramatically higher in gastric cancer tissues compared to adjacent nontumorous tissues." (PMID 29744291, 2018).
cervical carcinoma (53 papers, 2012 to 2026). A carcinoma arising from either the exocervical squamous epithelium or the endocervical glandular epithelium. "Remarkably, advanced cervical cancer with a higher expression of CDK2 as well as Cyclin A was linked to inferior survival, whereas both markers were down-regulated in response to chemotherapy." (PMID 36230567, 2022). "We suggested that loss of miR-1296 elevated CDK2 expression, which curtailed apoptosis of cervical cancer cells." (PMID 34284793, 2021). "Our study explored whether hsa_circ_0000520 can exert certain functions affecting the progression of cervical cancer in association with miR-1296 and CDK2, with intent to identify novel targets for cervical cancer treatment." (PMID 34284793, 2021). "CDK1 binds p21 with lower affinity than Cdk2, abrogating the postmitotic checkpoint in E6-expressing cells, favoring cervical cancer development through the induction of polyploidy." (PMID 41516135, 2025). "There was a significant downregulation of BCL-2 (p < 0.01), MDM2 (p < 0.0001), and CDK2 (p < 0.01) expression levels in the L. cornuta-treated cervical cancer cells compared to the NC." (PMID 39005932, 2024). "This demonstrated that inhibition of JNK-pathway activation reversed KLF14-induced CDK2 and CyclinA2 protein expression in cervical cancer cells." (PMID 38143751, 2023). "This showed that KLF14 increases CDK2 mRNA expression by activating the JNK pathway in cervical cancer cells." (PMID 38143751, 2023). "miR-509-3p has been shown to target CDK2 and to influence the cell cycle, colony formation, and migration of human lung and cervical cancer cell lines." (PMID 37386587, 2023). "The study also found that the supernatants of L. gasseri, L. crispatus, and L. jensenii can downregulate the expression of HPV oncogene E6 and E7, cyclin A, and cyclin-dependent kinase 2 (CDK2) to inhibit the activity of cervical cancer cells." (PMID 35800388, 2022). "According to the existing literature, CDK2 was a more promising therapeutic target for cervical cancer." (PMID 35994213, 2022). "Functional enrichment analyses and gene set enrichment analyses indicated that high mRNA expression of cyclin A2 (CCNA2) and cyclin-dependent kinase 2 (CDK2) stimulated cell cycle progression in cervical cancer." (PMID 35246013, 2022). "Notch1 induced cyclin D1 and CDK2 activity, two key molecules of cell proliferation in cervical cancer cells." (PMID 35740666, 2022). "In human cervical carcinoma cells, downregulation of CDK2 has been shown to induce tumor cell cycle arrest and cell apoptosis." (PMID 36428626, 2022). "The gene set enrichment analysis results of CCNA2 and CDK2 indicated that high mRNA expressions of CCNA2 and CDK2 stimulate cell cycle progression in cervical cancer." (PMID 35246013, 2022). "As for cyclin-dependent kinase 2 (CDK2), increased expression of CDK2 has been identified in the cervical cancer cell line HeLa as previously reported." (PMID 34284793, 2021). "Silencing hsa_circ_0000520 inhibited cervical cancer cell proliferation and promoted the inhibitory effects of miR-1296 on CDK2, thereby blocking cell cycle progression and promoting apoptosis." (PMID 34284793, 2021). "Hsa_circ_0000520 and cyclin-dependent kinase 2 (CDK2) were highly expressed in cervical cancer tissues." (PMID 34284793, 2021). "It was also shown that the positive expression rate of CDK2 in adjacent normal tissues was significantly lower than that in cervical cancer tissues." (PMID 34284793, 2021). "For example, in cervical cancer, circ_0084927 can adsorb miR-1179 to regulate CDK2 expression, promote cell proliferation and inhibit apoptosis." (PMID 33926347, 2021). "Polydatin efficiently inhibited cervical cancer cell proliferation by regulating cell cycle-related proteins including p21, p27, CDK2, CDK4, Cyclin D1, and Cyclin E1." (PMID 33912552, 2021). "Results of RT-qPCR revealed that the expression of CDK2 was increased in cervical cancer tissues compared with adjacent normal tissues." (PMID 34284793, 2021).
cervical carcinoma (continued). "Subsequently, we proved that hsa_circ_0000520-mediated inhibition of miR-1296 was able to promote CDK2 expression in cervical cancer." (PMID 34284793, 2021). "Further, the function of hsa_circ_0000520/miR-1296/CDK2 in cervical cancer was verified by performing in vivo experiments." (PMID 34284793, 2021). "Even though CDK2 had been studied thoroughly in cervical cancer, studies that focused on its networking with circRNAs were limited." (PMID 32699532, 2020). "This study demonstrated that Ary can restrict cervical cancer cells in G1/S phase along with cyclin A2 and Cdk2 expression increase." (PMID 27259234, 2016). "miR-509-3p has recently been shown to target CDK2 and to influence the cell cycle, colony formation and migration in human epithelial lung and cervical cancer cell lines." (PMID 27036018, 2016). "Overall, these data suggested that the activation of cyclin A2/CDK2 by HDAB contributed to S phase arrest in cervical cancer cells." (PMID 26041102, 2015). "HDAB treatment of cervical cancer cells resulted in S phase arrest and apoptosis, together with cyclin A2 and CDK2 upregulation." (PMID 26041102, 2015). "KLF14 promotes JNK-pathway activation and expression of CDK2 and CyclinA2 in cervical cancer cells." (PMID 38143751, 2023). "CDK2 protein expression was increased in the OE-KLF14 group compared with the control group (PSiHa=0.043, PHeLa<0.001), and CyclinA2 protein expression was increased (PSiHa=0.012, PHeLa=0.015), showing that KLF14 promoted CDK2 and CyclinA2 protein expression in cervical cancer cells." (PMID 38143751, 2023). "When extracted mRNA from the cells of the different groups for qRT-PCR, we observed that the expression of CDK2 mRNA in the OE-KLF14 group was increased compared with the control group (PSiHa<0.001, PHeLa<0.001), indicating that KLF14 promoted the expression of CDK2 mRNA in cervical cancer cells." (PMID 38143751, 2023). "Yet how miR-1296 affects CDK2 expression in cervical cancer is largely unknown according to prior reports." (PMID 34284793, 2021). "CDK inhibitor AT7519 could suppress phosphorylation of CDK1, CDK2 and RNA polymerase II in colon and cervical cancer cells as well as overcome chemoresistance." (PMID 34112144, 2021). "Besides, the expression of CDK2 and cyclin E1 increased in cervical cancer compared with adjacent normal tissues." (PMID 33516252, 2021). "In addition, the results of EdU and CCK-8 assays showed that proliferation of cervical cancer cells was suppressed by both miR-1296 inhibitor and sh-CDK2." (PMID 34284793, 2021). "Finally, to study the function of hsa_circ_0000520/miR-1296/CDK2 in cervical cancer in vivo, tumorigenesis in nude mice was developed." (PMID 34284793, 2021). "In summary, our results indicated that hsa_circ_0000520 could inhibit the expression of miR-1296 to upregulate CDK2, which further accelerated the proliferation of cervical cancer cells, promoted cell cycle and suppressed cell apoptosis." (PMID 34284793, 2021). "TCGA database further demonstrated that CDK2 was highly expressed in cervical cancer." (PMID 34284793, 2021). "Pharmacological or siRNA inhibition of the STIM1/Orai1 pathway of SOCE activation in human cervical cancer cells resulted in the decreased phosphorylation of CDK2 and the excursive expression of cyclin E, leading to autophagy accompanied with a cell cycle arrest in G1/S transition." (PMID 31252656, 2019). "The data further hint that CIP2A may be involved in the G1 checkpoint by regulating Cdk1 and Cdk2 in a B‐Myb–dependent manner in cervical cancer cells." (PMID 29893470, 2018).